TRIM28 (tripartite motif containing 28)
Diseases named in the same sentence as TRIM28 in open-access papers (continued):
Sharing a sentence is not in itself a finding about the gene and the disease.
neurodegenerative disease (3 papers, 2016 to 2024). A disorder of the central nervous system characterized by gradual and progressive loss of neural tissue and neurologic function. "Accumulation of DNA damage in neurons, a hallmark of neurodegenerative diseases such as Huntington's and Alzheimer's, can be facilitated by abnormalities in TRIM28 activity." (PMID 39534556, 2024). "Models of neurodegenerative disease in fruit flies and mice were then used to explore how TRIM28 affects the levels of tau and alpha-synuclein in animals." (PMID 27779468, 2016). "It will also be important to determine if this effect can be targeted, whilst leaving others roles of TRIM28 intact, in order to explore it as a potential target to treat or prevent neurodegenerative diseases." (PMID 27779468, 2016). "TRIM28 was also reported to stabilize and promote the accumulation of α-synuclein (α-Syn) and tau proteins in the nucleus of neurons, and promote the progression of neurodegenerative diseases." (PMID 34330324, 2021).
neurological disorder (3 papers, 2022 to 2024). "For example, TRIM28 controls the expression of transposable elements implicated in the regulation of human brain evolution and neurological disorder." (PMID 38433276, 2024). "Furthermore, TRIM28 is highly expressed in the CNS, and its transcriptional control is implicated in human brain evolution and neurological disorders." (PMID 35682642, 2022). "TRIM28 and SETDB1 are highly expressed in the CNS, participating in the differentiation of cell lineages within the brain, and their alterations or of their substrates have been found in several neurologic disorders." (PMID 36992419, 2023).
brain disorder (1 paper, 2025). A disease affecting the brain or part of the brain. "Thus, the conditions in which KZFPs, TRIM28, and TEs become dysregulated in the brain may contribute to our understanding of social dysfunction that characterizes many brain disorders." (PMID 41405865, 2025).
genetic diseases (1 paper, 2022). "TRIM28 is an important player in ovarian physiology and therefore, might also have a potential role in genetic diseases causing reproductive disorders." (PMID 35906245, 2022).
psychiatric disorder (1 paper, 2021). A disorder characterized by behavioral and/or psychological abnormalities, often accompanied by physical symptoms. "Trim28 is highly expressed in the brain and has been linked to behavioral phenotypes reminiscent of psychiatric disorders." (PMID 33644903, 2021).
TRIM28 also shares sentences with these, for which no sentence is quoted: Alzheimer disease (2 papers); amyotrophic lateral sclerosis (2); celiac disease (2); head and neck cancer (2); multiple myeloma (2); myositis (2); nasopharyngeal carcinoma (2); s sarcoma (2); uveal melanoma (2); abscesses (1); adenocarcinoma (1); adrenocortical carcinoma (1); Allergy (1); atherosclerosis (1); autism spectrum disorder (1); bladder urothelial carcinoma (1); blood cancer (1); brain cancer (1); Burkitt lymphoma (1); Charcot-Marie-Tooth disease (1); cognitive deficits (1); Crohn disease (1); dermatomyositis (1); Diarrhea (1); epilepsy (1); Ewing sarcoma (1); fibroid tumors of (1); Glucose intolerance (1); Hypertension (1); Immune Thrombocytopenia (1).
A further 25 diseases each share a sentence with TRIM28 in 1 paper.